SAV1 (salvador family WW domain containing protein 1)
Diseases named in the same sentence as SAV1 in open-access papers (continued):
Sharing a sentence is not in itself a finding about the gene and the disease.
cancer (28 papers, 2008 to 2025). A tumor composed of atypical neoplastic, often pleomorphic cells that invade other tissues. "The SAV1 gene is infrequently mutated in human cancers; however, its expression in cancer tissue is frequently downregulated either epigenetically or post transcriptionally." (PMID 32439835, 2020). "SAV1 deficiency in cells promotes tumorigenesis and cancer metastasis, and is closely associated with poor prognosis for cancer patients." (PMID 32439835, 2020). "We further identify cancer-associated SAV1 mutations with impaired ability to bind Akt, leading to Akt hyperactivation." (PMID 30944303, 2019). "Consistently, amplification of YAP or loss-of-function mutation of Hippo pathway components such as MOB1 and SAV1 have been identified in a series of human cancers." (PMID 26561204, 2015). "Mutations in SAV1 lead to Akt hyperactivation and uncontrolled cancer growth." (PMID 39123485, 2024). "The deficiency of SAV1 in cancer cells causes the MST1/2 proteins to be inactive." (PMID 32439835, 2020). "Deletion of Sav1 in the murine liver causes hepatomegaly and cancer after a latency of 1 year." (PMID 31338332, 2019). "Notably, SAV1 deficiency is closely associated with poor prognosis for cancer patients." (PMID 32439835, 2020). "Early evidence of a role for the Hippo pathway in cancer came from studies whereby the human orthologue of Salvador (SAV1), a founding member of the Drosophila Hippo pathway, were found to be mutated in renal cancer cell lines." (PMID 39103676, 2024). "Undoubtedly, the mechanisms regulating the SAV1 protein level require further investigations, especially since reports on SAV1 protein expression in various cancers are inconsistent." (PMID 38136317, 2023). "The tumor suppressor SAV1 expression is downregulated in various malignant tumors, including lung cancer, and results in robust tumorigenicity." (PMID 32439835, 2020). "Our study found that SAV1 is an excellent target for cancer therapy, and this approach has several advantages." (PMID 32439835, 2020). "We found that treating SPC-A-1 cells with MG132, a ubiquitination–proteasome inhibitor, increased SAV1 levels and that lycorine treatment further increased SAV1 protein levels in cancer cells in the presence of MG132." (PMID 32439835, 2020). "Lycorine markedly increased SAV1 levels in cancer cells by inhibiting SAV1 degradation via the ubiquitin–lysosome system." (PMID 32439835, 2020). "SAV1 levels were significantly lower in most cancer cell lines." (PMID 37033161, 2023). "One of these genes, Sav1, had been previously used to predispose for cancer in an SB model but had not been identified as a candidate driver in an SB hepatocellular screen." (PMID 31338332, 2019). "Consistent with this notion, unlike WT-SAV1, the cancer-associated SAV1-R233Q mutant was largely resistant to MERTK inhibitor -mediated suppression of Akt activation and displayed less sensitivity to UNC2025." (PMID 30944303, 2019). "Altogether, these findings suggest that SAV1 may be expressed in a cancer-type-specific manner." (PMID 38136317, 2023). "Thus, the roles of SAV1 in cancer have gained increasing attention." (PMID 37033161, 2023). "Therefore, SAV1 was at low expression in cancer cells, compared to normal lung epithelial cells." (PMID 35864957, 2022). "FTase proteins (FNTA and FNTB) as well as eight of the 116 PFPs are known cancer-relevant proteins as per COSMIC Cancer Gene Census49 or TCGA50 (KRAS, HRAS, NRAS, RHEB, RHOA, DDX3X, ARID2, and SAV1)." (PMID 39995872, 2025). "But in cancer cells, they override the negative regulation of MST1/2, LATS1/2, MOB1 and SAV1, and result in inactivation of Hippo kinase cascade which leads to nuclear translocation of YAP and TAZ and the expression of downstream targets." (PMID 31941533, 2020). "However, there are no reported therapeutics that correct SAV1 deficiency in cancer." (PMID 32439835, 2020). "However, investigation of therapeutic strategies to target SAV1 deficiency in cancer is lacking." (PMID 32439835, 2020).
cancer (continued). "Whole genome and transcriptome sequencing of mucinous tubular and spindle cell RCC carcinomas (a rare cancer type) also revealed correlations between loss of Hippo pathway tumor suppressor genes such as NF2 and SAV1 and YAP1 nuclear accumulation during cancer progression." (PMID 39123485, 2024). "Besides, exogenous overexpression of SAV1 can act as a traffic protein, activating the Hippo signaling and concurrently inhibiting the WNT pathway to decrease cancer cell growth." (PMID 35864957, 2022). "We found smoking cancer patients with high expression of SAV1 had a higher OS rate and exhibited a slight trend in the nonsmokers, implying that smoking cancer patients with higher SAV1 appeared to have a better prognosis." (PMID 35864957, 2022). "Therefore, upregulation of SAV1 expression and subsequent activation of the MST1/2-LAST1/2 complex in cancer cells are important treatment strategies to be explored." (PMID 32439835, 2020). "To further investigate the contribution of the MERTK/Akt/SAV1 signaling in Akt activation triggered by growth signaling such as PI3K, we ectopically expressed a cancer patient-derived constitutively active H1047R-PIK3CA mutant in RCC cells depleted of endogenous SAV1." (PMID 30944303, 2019). "However, how cancer cells override the negative regulation induced by MST1, LATS2, MOB1, and SAV1 to exhibit constitutively inactivated Hippo signaling and activated YAP/TAZ remains puzzling." (PMID 26561204, 2015). "Deregulation of the Hippo pathway is one event contributing to cancer development and leading to a kinase cascade in which macrophage stimulating 1/2 kinases (MST1/2) phosphorylate large tumor suppressor kinase 1/2 (LATS1/2) and Salvador family WW domain containing protein 1 (SAV1)." (PMID 38388496, 2024). "SAV1 expression in nonmalignant tissue was much higher than in cancer tissue." (PMID 28968962, 2017). "However, how MST1/2, LATS1/2, SAV1, and MOB1 are simultaneously repressed to exhibit constitutively activated YAP/TAZ in cancer remains unclear." (PMID 26561204, 2015).
infection (5 papers, 2011 to 2022). The state of being infected such as from the introduction of a foreign agent such as serum, vaccine, antigenic substance or organism. "In contrast, LG-1 cells were susceptible to infection by SAV1, fish nodavirus (BFNNV genotype), IHNV genogroup M and VHSV genogroup III, resulting in typical cytopathic effect (CPE) and the distinct cellular expression of viral antigens." (PMID 34572091, 2021). "The mortalities experienced during experimental infections with SAV1 are highly variable and unpredictable, although the average level of mortality seen in the present study was within the reported range for mortalities during a natural outbreak of PD." (PMID 28949966, 2017). "Cano and others recently established an SAV1 infection in Atlantic salmon fry using an immersion route of infection." (PMID 28949966, 2017). "This study was performed to examine the susceptibility and pattern of disease pathogenesis in diploid and triploid Atlantic salmon fry exposed to SAV1 through an IP, immersion or co-habitation route of infection." (PMID 28949966, 2017). "The CHH-1 cell line develops CPE faster than CHSE-214 and Salmon head kidney-1 (SHK-1) cells after infection with SAV1." (PMID 25009976, 2014). "The aim of the present study was to evaluate the effects of an SAV1 infection in triploid Atlantic salmon fry relative to diploid fry, comparing their susceptibility to SAV1 infection and the disease pathogenesis that resulted using different routes of infection." (PMID 28949966, 2017).
colonic polyps (2 papers, 2020 to 2023). "A similar phenotype is observed in the Sav1-depleted intestine; upon the loss of Sav1, crypts become enlarged and disoriented which in turn develops into the colonic polyps." (PMID 33271948, 2020). "Moreover, Sav1 knockout mice were shown to develop colonic polyps at 13 months, similar to sessile serrated polyps observed in human lesions and chemically-induced intestinal injury further aggravated the tumorigenicity of these mice." (PMID 33271948, 2020). "The study also proved that this effect was YAP -dependent, given that mice with intestinal epithelium-specific knockout of Sav1 with YAP did not exhibit the formation of colonic polyps." (PMID 33271948, 2020).
cardiac disease (1 paper, 2020). "Using gain- and loss-of-function genetic models, it was shown that the Hippo-YAP signaling pathway components Mst1/2, Sav1, Lats1/2, NF2, and downstream transcriptional regulators YAP and Tead1 regulate cardiac gene expression, cardiomyocyte proliferation, and cardiac disease status." (PMID 32938943, 2020).
SAV1 also shares sentences with these, for which no sentence is quoted: gastroenteritis (6 papers); age (4); ciliopathy (2); myocardial infarction (2); acute kidney injury (1); carcinoma in situ (1); cardiac arrhythmia (1); cervical squamous cell carcinoma (1); cholangiocarcinoma (1); colitis (1); COVID-19 (1); diarrheal disease (1); ischemia (1); lipid metabolism disorders (1); liver (1); lung squamous cell carcinoma (1); metastatic cancer (1); nephronophthisis (1); non-alcoholic fatty liver disease (1); Obesity (1); ocular surface squamous neoplasia (1); osteosarcoma (1); papillary renal cell carcinoma (1); pneumonia (1); premature ovarian failure (1); sessile serrated polyp (1); soft tissue sarcoma (1); thyroid (1); type 2 diabetes mellitus (1); ventricular septal defect (1).
A further 1 disease shares a sentence with SAV1 in 1 paper.